RCC1 (regulator of chromosome condensation 1)
Diseases named in the same sentence as RCC1 in open-access papers (continued):
Sharing a sentence is not in itself a finding about the gene and the disease.
cancer (43 papers, 2007 to 2025). A tumor composed of atypical neoplastic, often pleomorphic cells that invade other tissues. "This highlights RCC1’s critical function in evading programmed cell death, a hallmark of cancer resilience." (PMID 40163507, 2025). "RCC1’s overexpression in several cancer types and its association with aggressive phenotypes suggest its potential as a prognostic biomarker, though further validation is required." (PMID 40163507, 2025). "To evaluate RCC1’s role in sustained cell proliferation, we conducted soft agar colony formation assays, which measure anchorage-independent growth—a hallmark of cancer aggressiveness." (PMID 40163507, 2025). "RCC1 proteins are implicated in the initiation and progression of a variety of cancers by promoting nuclear entry and accumulation of β-catenin." (PMID 36909424, 2023). "The landscape of RCC1/SNHG3/SNHG12 associated with various immune infiltrations in human cancers was demonstrated using TIMER2.0." (PMID 36148010, 2022). "RCC1/SNHG3/SNHG12 are not only highly expressed in a variety of cancers, but also are risk factors for poor prognosis." (PMID 36148010, 2022). "In particular, the conducted analysis reveals the relation of RCC1 to multiple immune checkpoint genes and suggests that the regulation of RCC1 is closely related to tumor infiltration of cancer-associated fibroblasts and CD8+ T cells." (PMID 34298996, 2021). "Although experimental studies still need to confirm its potential as a neoantigen, these data suggest RCC1 as a new target for cancer vaccines especially in UCEC due to the most frequent mutations in UCEC." (PMID 34298996, 2021). "Due to its ability to prevent multiple replication of S-phase DNA, many studies in humans have shown that RCC1 is associated with cancer." (PMID 30965557, 2019). "Given that enhanced DDR is a hallmark of chemoresistant cancer cells, we investigated whether RCC1 contributes to this process in CRC." (PMID 41281944, 2025). "Higher expression of RCC1 is positively associated with cancer progression and poor prognosis." (PMID 38561375, 2024). "Based on the EPIC, MCPCOUNTER, XCELL, TIDE, TIMER, CIBERSORT, CIBERSORT-ABS and QUANTISEQ algorithms, the correlation between the expression of RCC1 and cancer-associated fibroblasts (CAF) and the infiltration level of CD8+ T-cells were estimated in different TCGA cohort tumors." (PMID 34298996, 2021). "RCC1 may be used as a lone indicator or in conjunction with other biomarkers for screening to assess cancer risk and cancer progression for prediction and prognosis, respectively." (PMID 33102517, 2020). "In animals, RCC1 is responsible for activating Ran and linked to many biological processes coupled with Ran, such as nucleo-cytoplasmic transport, mitosis, nuclear-envelope assembly, repair of DNA damage, and incidences of cancer." (PMID 30965557, 2019). "Thus, the role of RCC1 in tumorigenesis might depend on the cargo proteins it associates with in specific cancer types." (PMID 38561375, 2024). "This aligns with prior studies showing that RCC1 expression promotes the dysregulated G1/S cell cycle transition commonly observed in cancer." (PMID 40163507, 2025). "Although the role of RCC1 in CRC remains underexplored, prior studies have implicated it in cancer progression and prognosis." (PMID 41281944, 2025). "Given its multifaceted roles, RCC1 warrants further investigation as a potential therapeutic target in cancer research." (PMID 40163507, 2025). "Such a panel would allow clinicians to tailor treatment strategies based on RCC1 expression levels, enabling more personalized approaches to cancer care." (PMID 40163507, 2025).
cancer (continued). "Future studies should explore RCC1’s impact on other cancer types, evaluate its interactions with therapeutic agents, and investigate combination strategies to enhance efficacy, particularly in immune-sensitive cancers." (PMID 40163507, 2025). "Bcl2 prevents mitochondrial membrane permeabilization, a critical step in apoptosis initiation, and its downregulation following RCC1 knockdown underscores RCC1’s role in modulating anti-apoptotic mechanisms to promote cancer cell survival." (PMID 40163507, 2025). "This study not only elucidates the critical functions of RCC1 in cancer biology but also provides a foundation for future research into its role across various cancer types and interactions with therapeutic agents." (PMID 40163507, 2025). "RCC1’s primary function in cell cycle regulation is particularly significant for cancer progression." (PMID 40163507, 2025). "Targeting RCC1 offers a dual advantage: disrupting cancer growth and enhancing apoptotic pathways, creating an exciting opportunity for precision therapies." (PMID 40163507, 2025). "Our findings provide substantial evidence of RCC1’s involvement in key aspects of cancer cell biology." (PMID 40163507, 2025). "RCC1 inhibition decreased cancer cell viability, invasion, and colony formation while inducing apoptosis, making it a promising candidate for targeted therapies." (PMID 40163507, 2025). "RCC1 appears to facilitate these processes by enhancing cancer cell dissemination and tissue infiltration." (PMID 40163507, 2025). "By promoting survival, proliferation, and metastatic behavior, RCC1 acts as a central regulator in cancer progression." (PMID 40163507, 2025). "Recent studies have identified RCC1 as a potential oncogene, with elevated expression levels observed in multiple cancer types, including breast, lung, ovarian, and colorectal cancers." (PMID 40163507, 2025). "Similar to observations in other cancers, we found that RCC1 knockdown induced G0/G1 arrest and suppressed proliferation in both parental and resistant CRC cells." (PMID 41281944, 2025). "In cancer cells, overexpression of RCC1 disrupts these checkpoints, allowing uncontrolled progression through mitosis and contributing to rapid proliferation, a hallmark of tumorigenesis." (PMID 40163507, 2025). "Matrigel invasion assays corroborated these results, indicating that RCC1 silencing significantly reduced the invasive capacity of cancer cells." (PMID 40163507, 2025). "The reduced viability and colony formation observed upon RCC1 knockdown suggest its role in supporting unregulated cell cycle progression in cancer cells." (PMID 40163507, 2025). "By illuminating RCC1’s integration into survival networks, this study not only advances our understanding of cancer biology but also lays the groundwork for innovative treatments aimed at halting cancer progression and metastasis." (PMID 40163507, 2025). "By acting as a GEF for Ran, RCC1 facilitates cell cycle progression and apoptosis resistance, enabling cancer cells to thrive under stress conditions." (PMID 40163507, 2025). "Given its role in regulating the cell cycle, apoptosis resistance, and metastatic behavior, RCC1 represents a potential target for further investigation in cancer therapy." (PMID 40163507, 2025). "RCC1’s interactions with survival-promoting signaling cascades further support cancer cell resilience, emphasizing its potential role in oncogenesis." (PMID 40163507, 2025). "Our previous studies have shown that RCC1 is frequently upregulated in various cancer types compared with adjacent normal tissues, with its upregulation linked to enhanced tumor proliferation and progression." (PMID 41281944, 2025). "Among the top 4 cancer types with highest T/N ratio of RCC1 expression (THYM, GBM, DLBC, SARC), only SARC is identified with a significant reduced survival in patients." (PMID 38561375, 2024).
cancer (continued). "The expression of SNHG3 and SNHG12 in pan-cancer showed high similarity with the expression of RCC1." (PMID 36148010, 2022). "In a study of non-small cell lung cancer, knockdown of RCC1 not only significantly inhibited the proliferation of cancer cells but also reduced the volume and weight of tumor models after PD-L1 monoclonal antibody treatment." (PMID 36148010, 2022). "We evaluated the expression of RCC1/SNHG3/SNHG12 in 33 different cancer types using several databases such as GEPIA, UALCAN, and TIMER2.0, and found that they were significantly differentially expressed in tumor tissues and normal tissues." (PMID 36148010, 2022). "High expression of RCC1/SNHG3/SNHG12 in patients with a variety of cancers including ACC, KIRP, LAML, LGG, LIHC, and PRAD predicted lower overall survival and disease free survival." (PMID 36148010, 2022). "In the analysis RCC1/SNHG3/SNHG12 as a signature for drug-target response difference and association in pan-cancer, Topotecan, TKI258 and Paclitaxal were found which showed significant differences in different expression levels." (PMID 36148010, 2022). "High expression of RCC1/SNHG3/SNHG12 was poor in early DFS in pan-cancer and correlated with low DFS in ACC, LGG, LIHC, and PRAD." (PMID 36148010, 2022). "Based on this property, a growing number of experiments have shown that RCC1 is aberrantly expressed in many diseases and plays a regulatory role in cancer progression." (PMID 36148010, 2022). "The analysis of TCGA and CPTAC data showed that RCC1 expression was significantly upregulated in a variety of cancers, and was higher in some cancer stage III and IV patient samples than in stage I and II." (PMID 36148010, 2022). "Overall, RCC1/SNHG3/SNHG12 can be used as a marker of poor prognosis in the early stages of pan-cancer." (PMID 36148010, 2022). "In the analysis of RCC1, we found that the three are highly consistent in pan-cancer, including expression levels, survival, and participation in cellular processes." (PMID 36148010, 2022). "Meanwhile, combined with the results of survival analysis, the role of RCC1/SNHG3/SNHG12 in some cancers is dominated by suppression of immune response." (PMID 36148010, 2022). "In this genome database study, based on The Cancer Genome Atlas, Genotype-Tissue Expression and Gene Expression Omnibus databases, the potential role of RCC1 in 33 tumors’ entities was explored." (PMID 34298996, 2021). "In order to understand the relationship between RCC1 and cancer, we elucidated the expression level of RCC1 in different tumour types." (PMID 33630417, 2021). "The results show that RCC1 is highly expressed in most human malignant neoplasms in contrast to healthy tissues." (PMID 34298996, 2021). "In recent years, an increasing number of studies have found that RCC1 is related to cell cycle, DNA damage, and cancer." (PMID 33102517, 2020). "The abnormal expression of RCC1 in a variety of malignant tumors suggests its potential as a cancer biomarker." (PMID 33102517, 2020). "In conclusion, although RCC1 is still rarely used directly in the clinical diagnosis of cancer, it is valuable to determine the reference normal range of RCC1 in various tissues." (PMID 33102517, 2020). "Furthermore, the observed decrease in metastatic behavior in RCC1-silenced cells suggests its involvement in cell adhesion and motility, essential for cancer dissemination." (PMID 40163507, 2025). "The insights gained from this study may reveal novel therapeutic avenues for targeting RCC1 in cancer treatment." (PMID 40163507, 2025).
cancer (continued). "By targeting RCC1-dependent cancer survival mechanisms, combination therapies with RCC1 inhibitors and standard chemotherapeutics could provide robust treatment options, enhance therapeutic outcomes, and address chemoresistance challenges." (PMID 40163507, 2025). "Given its involvement in central cancer progression mechanisms such as cell cycle regulation, apoptosis resistance, and metastatic behavior, it is hypothesized that RCC1 may drive the aggressive phenotypes observed in these cancers." (PMID 40163507, 2025). "Overall, RCC1’s multifunctional role in cancer survival and progression suggests it may be a potential biomarker and therapeutic target, though further preclinical and clinical research is needed." (PMID 40163507, 2025). "Combining RCC1-targeted therapies with existing treatment regimens could enhance therapeutic efficacy and overcome drug resistance in aggressive cancers." (PMID 40163507, 2025). "Further studies are needed to determine whether RCC1 inhibition, in combination with other treatments such as chemotherapeutics or targeted agents, could influence cancer cell proliferation and metastasis." (PMID 40163507, 2025). "We hypothesized that RCC1 knockdown would lead to decreased cancer cell viability, migration, and invasion, along with increased apoptotic responses." (PMID 40163507, 2025). "Knockdown experiments demonstrated that RCC1 suppression impairs cancer cell survival and invasiveness in vitro, suggesting that targeting RCC1 could provide insights into its role in oncogenic pathways." (PMID 40163507, 2025). "Our study showed that RCC1 could mediate the down-regulation of SIRT3 expression in KRAS-driven cancer cells." (PMID 41391757, 2025). "Incorporating RCC1 into biomarker panels, alongside SGOL2 and USP53, could improve diagnostic accuracy and enable more effective, targeted cancer treatments." (PMID 40163507, 2025). "When combined with existing treatment regimens, RCC1 inhibitors could enhance efficacy, especially in cancers with high RCC1 expression." (PMID 40163507, 2025). "This suggests that targeting RCC1 might have potential in combinatory therapy with first-line anti-cancer drugs like EGFR inhibitors, mTOR inhibitors and AR inhibitors, whose effectiveness are often compromised by increased cytoplasmic distribution of Skp2." (PMID 38561375, 2024). "Our findings unveil a new role of RCC1 in promoting the nucleo-cytoplasmic trafficking of oncogenic Skp2 protein, the process of which is commonly observed and correlated with the progression of many types of cancer." (PMID 38561375, 2024). "The expression level of RCC1 was reported to be elevated in multiple types of cancers." (PMID 38561375, 2024). "Patients with high RCC1/SNHG3/SNHG12 expression in pan-cancer have poor early OS." (PMID 36148010, 2022). "The pan-cancer correlations between RCC1/SNHG3/SNHG12 and immune checkpoints were displayed." (PMID 36148010, 2022). "Interestingly, endogenous RCC1 expression in primary carcinoma cells and in liver metastases were linearly positively correlated." (PMID 34924821, 2021). "Finally, by analyzing the change in gene expression between normal and transformed tissue in each cancer, we found that tumors are characterized by an imbalance of RCC1 and RanGAP1 in favor of Ran activation." (PMID 32528950, 2020). "For cancers not caused by RCC1 mutations, RCC1 appears to respond to tumor cycle progression through increased expression." (PMID 33102517, 2020). "Therefore, even though there have been relatively few published reports, the biological function of RCC1 and its overexpression in multiple types of cancer appears to be relatively consistent." (PMID 33102517, 2020).
cancer (continued). "Abundant evidence indicates that RCC1 is more consistent with the role of an intermediate effector protein in tumors, and its high expression is misled by upstream signals, thus promoting the cell cycle of cancer cells." (PMID 33102517, 2020). "Similarly, the absence of mutations in the tumor suppressor PTEN in many types of human cancers also leads to increased RCC1 expression." (PMID 33102517, 2020). "The high expression of RCC1 in cancer cells accelerates the cell cycle and DNA repair, and, as such, tumor cells may regulate cell mitosis by increasing the expression of RCC1." (PMID 33102517, 2020). "Collectively, these findings suggest that RCC1 overexpression may lead to chemoresistance by accelerating cell cycle progression and DNA repair, highlighting its potential as a compelling therapeutic target for overcoming chemoresistance in cancer therapy." (PMID 41281944, 2025). "Targeting RCC1 in cancer models may help elucidate its role in oncogenic pathways, offering insights into potential therapeutic strategies for aggressive and treatment-resistant cancers." (PMID 40163507, 2025). "Furthermore, little is known about the relationship between RCC1 and carcinomas." (PMID 29789527, 2018). "The Regulator of Chromosome Condensation 1 (RCC1), a master regulator of cell cycle progression, chromatin structure, and nuclear transport, emerges as a powerful driver of cancer progression." (PMID 40163507, 2025). "Previous studies have explored the mechanism of RCC1 and RCC2 in other kinds of cancers, which is mainly ascribed to its regulation of numerous signaling pathways." (PMID 38434981, 2024). "Of note, It was revealed that the expression of most genes was generally consistent with results of TCGA cancer set, such as TRIM24, HMG20B, CBX6, IDH1, RCC1, RYBP, CBX7, and LBR." (PMID 36246611, 2022). "Furthermore, by analyzing the expression of two essential partners of Ran involved in GTP loading (RCC1) and hydrolysis (RanGAP1), we found that while the RCC1 gene is clearly overexpressed in 16 of 18 studied cancers, the dysregulation of RanGAP1 is cancer dependent." (PMID 32528950, 2020). "Therefore, in cancers that do not possess a mutated RCC1, it may be possible to induce cell cycle arrest, as well as senescence or apoptosis of cancer cells by lowering the expression of RCC1." (PMID 33102517, 2020). "RCC1, along with genes like SGOL2 and USP53, could form a prognostic biomarker panel to assess cancer aggressiveness and predict patient outcomes." (PMID 40163507, 2025). "Although there is growing evidence to support the relationship between RCC1 and cancer, detailed pancancer analyses have not yet been performed." (PMID 34298996, 2021). "RCC1 functions as a key regulator of the Ran GTPase cycle, influencing nucleocytoplasmic transport, mitotic spindle assembly, and chromatin dynamics processes that are not exclusive to cancer cells but are also crucial for normal cellular homeostasis." (PMID 40163507, 2025). "After validating the non-degradable characteristic of Skp2AA, we further conducted a series of functional experiments in vitro to study whether expression of non-degradable Skp2AA would resume the cancer progression of RCC1 knockdown cells." (PMID 38561375, 2024). "Additionally, our study revealed that NTMT1, which methylates the α-N-terminal amines of proteins [e.g., RCC1 (regulator of chromosome condensation 1), CENPA (centromere protein A), and DDB2 (damage specific DNA binding protein 2)], likely possesses cancer-promoting roles." (PMID 34285249, 2021).